CASP8 (caspase 8)
Diseases named in the same sentence as CASP8 in open-access papers (continued):
Sharing a sentence is not in itself a finding about the gene and the disease.
cancer (continued). "In the spleen, 8/84 cancer-related genes were affected in FLT mice compared to AEM controls (P<0.05; up: Cdkn2a; down: Birc5, Casp8, Ctnnb1, Map2k1, Mdm2, NFkB1, Pdgfa)." (PMID 24069384, 2013). "Apo2L/TRAIL induces apoptosis in cancer cells through interactions with death receptor 4 (DR4) and DR5, which form the death-inducing signal complex (DISC) by binding to FADD and caspase-8 or caspase-10." (PMID 22666346, 2012). "It has been known that c-Myc renders cancer cells sensitive to TRAIL-induced apoptosis by the up-regulation of DR5, the activation of caspase-8, and the down-regulation of c-FLIP and Mcl-1." (PMID 21513580, 2011). "Western blot analysis showed that treatment with 1 μM NSC-743380 effectively activated caspase-8 and caspase 9 in MCF-7 and A498 cells, indicating that its cytotoxic effect in cancer cells is due to its induction of apoptosis." (PMID 22174819, 2011). "More specifically, raw crushed garlic is high in allicin, a powerful bioactive compound of garlic that induced activation of CASP3, CASP8 and CASP9 and cleavage of poly (ADP-ribose) polymerase in several cancer cells." (PMID 19552815, 2009). "In cancer cells, IGFBP-5 activated the caspase-8 signal transduction pathway, increased the structure sensitivity to TNF-α, and induced the internal apoptosis pathway." (PMID 19476635, 2009). "The proposed mechanism of action involves the induction of caspase-8-dependent apoptosis by the pro-apoptotic tumor necrosis factor-related apoptosis-inducing ligand (TRAIL), mediated by death receptors 4 and 5 (DR4 and DR5, respectively) on cancer cells." (PMID 41373826, 2025). "In HT-29 cancer cell lines, Caspase-3/7 activity increased, while Caspase-8 and Caspase-9 activity decreased compared to the negative control." (PMID 40872562, 2025). "• Exertion of anticancer effects through 3 major pathways: apoptosis (BIRC3, BIRC5, caspase-8, caspase-9, and PARP1), transcriptional dysregulation in cancer (CDKN1A, CDKN1B, MMP9, MYC, JUN, and RELA), and cancer progression (caspase-3, CCND1, CTNNB1, VEGFA, and Wnt-1)." (PMID 39181121, 2025). "The bioactivity test showed that serratiochelin B displayed weak but selective cytotoxicity against HepG2 cancer cells with an IC50 of 50.6 μmol/L and could trigger apoptosis through both Bcl-2/Bax/caspase-3 and Fas/FasL/caspase-8 signaling pathways." (PMID 40559650, 2025). "The Cancer Genome Atlas and other studies have identified HRAS, CASP8, and NOTCH1 mutations in human papillomavirus-negative, EGFR-negative HNSCC." (PMID 41463200, 2025). "We show here that jacaranone enhances TNFα-induced apoptosis and induce caspase-8 activation in cancer cells." (PMID 39769432, 2024). "In diverse cancer lineages (colon and lung cancer, melanoma, and leukemia), the synergistic action of TNF-α and IFN-γ can trigger the activation of a variety of signaling switches such as GSDMD, GSDME, caspase-8, and MLKL." (PMID 38553639, 2024). "Taking into account that phosphorylation generally impairs apoptotic signaling, it is no surprise then that caspase-8 phosphorylation has been shown to be upregulated in several human cancers." (PMID 39513921, 2024). "Our recent study showed that gasdermin C (GSDMC) cleavage by caspase-8 switched apoptosis to pyroptosis in triple-negative breast cancer (TNBC) and other cancer types, indicating that olaparib may trigger pyroptosis in GSDMC-positive TNBC cells." (PMID 37883181, 2024). "Sinapic acid is a potent anti-oxidant used for the treatment of cancer, infections, oxidative stress, and inflammation; its anti-cancer mechanism works through the regulation of multiple proteins (CTNNB1, PRKCA, CASP8, SIRT1) and cytochrome enzymes (CYP1A1, CYP3A4)." (PMID 38999065, 2024). "It was also observed that TNF-α, CASP8, CLIP3, and STAT1 are characteristics of G2 and G3 cancer." (PMID 37233761, 2023). "Additionally, tumor suppressors caspase 8 (CASP8) and caspase 9 (CASP9) are phosphorylated by CDK1 facilitating apoptosis in cancer cells." (PMID 37311884, 2023).
cancer (continued). "Although the functional domains required for aggregation and cell death are the same as in cancer cells, Bax∆2 relied on SGs, not caspase 8, for neuronal cell death." (PMID 37371550, 2023). "Further studies are needed to deepen this issue and to clarify the link between RTKs and Caspase-8 non-apoptotic functions in cancers." (PMID 37444381, 2023). "Additionally, LCA promoted apoptosis in cancer cells by increasing the expression of cleaved PARP and cleaved caspase-8, which are key proteins involved in programmed cell death." (PMID 38140059, 2023). "Our findings showed that BHE and betanin can stimulate the intrinsic and extrinsic apoptosis pathways in HT-29 and Caco-2 cancer cell lines via downregulation of Bcl-2 and upregulation of BAD and Caspase-9 genes and also upregulation of Fas-R, Caspase-3, and Caspase-8, respectively." (PMID 37464362, 2023). "The results showed that CASP8 protein expression was found to be considerably correlated with the degree of differentiation and lymph node metastasis and that it was higher in ESCA cancer tissues than in nearby normal tissues." (PMID 36533709, 2023). "Cancer cells require FADD (an adapter protein) and caspase-8 for apoptosis mediated by DR4 and DR5." (PMID 37065863, 2023). "Other studies indicated that RES induced apoptosis in various cancer cell lines and TNBC cell lines through extrinsic and intrinsic pathways by activating caspase-8 and 9; however, the major pathway of RES is intrinsic through activation of caspase-9-dependent mitochondria pathways." (PMID 35163062, 2022). "Therefore, we performed the perturbation expression of pyroptosis regulators across another nearly 10,000 samples, representing 33 cancer types, and observed CASP3, CASP4, CASP8, and GSDMD were highly expressed in cancer cells." (PMID 35620284, 2022). "We observed that NLRP7 (n = 8), AIM2 (n = 10), CASP8 (n = 6), GSDMA (n = 5), GSDMB (n = 8), and GSDMC (n = 12) mainly showed hypomethylation in most cancers, and PLCG1 (n = 11), NLRP6 (n = 13), ELANE (n = 11), CASP6 (n = 5), NLRC4 (n = 12), and PYCARD (n = 8) showed hypermethylation in most cancers." (PMID 35246158, 2022). "However, a later study demonstrated that a major effect of autophagy in cancer cells is to inhibit TNFα and TRAIL-induced apoptosis by reducing FADD-dependent caspase-8 activation." (PMID 35401556, 2022). "Intriguingly, the down-regulation of Caspase-8’s activity has been shown to be beneficial for several cancers due to its involvement in non-apoptotic functions like cell-cycle regulation, proliferation, angiogenesis, and chemotherapy resistance." (PMID 36399280, 2022). "Hypomethylation across cancers was observed for AIM2, CASP8, GZMA, and IL-1B." (PMID 36605187, 2022). "Indeed, the ratio of caspase-8 to FLIP, or caspase-8 to MCL-1 were more predictive of response to MEDI3039 in several major cancer types compared with single biomarker analyses when using either protein or mRNA expression levels." (PMID 35086954, 2022). "Similar to other carcinoma, in EC various tumor suppressor gene promotors (MLH1, PTEN, p16, APC, MGMT, RASSF1, PR and CDH1) are hypermethylated, whereas oncogene promotors (BMP, CTCFL, PARP1, CASP8) are hypo- or demethylated." (PMID 35284957, 2022). "Intrinsic TRAIL resistance of cancer cells has been attributed to such factors such as high levels of decoy receptors and the presence of anti-apoptotic proteins, such as FLIP, which can inhibit caspase-8 activation at the DISC." (PMID 34073507, 2021).
cancer (continued). "Ultimately, activation of caspase-8 activates executioner caspase-3 that mediates apoptotic cell death CHOP is known as an apoptotic inducer through endoplasmic reticulum (ER) stress and that depletion of CHOP prevents apoptosis against various cancer drugs." (PMID 34710995, 2021). "We found that different cancer cell lines exhibited distinct responses, including sensitivity and insensitivity, to DM-αKG-induced pyroptosis, and that these responses seemed to be unrelated to the expression of MDH1, DR6, caspase-8, and GSDMC." (PMID 34012073, 2021). "Taken together, our data suggest that LMP with its deadly consequences represents a “default” death mechanism in cancer cells, when Caspase-8 is absent and apoptosis cannot be induced." (PMID 34011952, 2021). "The three clusters generated contained genes or proteins involved in apoptosis (BIRC3, BIRC5, PARP1, CASP8, and CASP9), transcriptional dysregulation in cancer (CDKN1B, RELA, CDKN1A, MYC, JUN, and MMP9), and cancer progression (CCND1, CASP3, CTNNB1, WNT1, and VEGFA) pathways." (PMID 34836311, 2021). "Notably, three of the medicines studied (excluding ASLRB) interacted with caspases in its anti-cancer mechanisms, with RJL and PK extract regulating caspase-3 expression among other pro-apoptotic genes while Harmol activated caspase-8." (PMID 33985540, 2021). "The presence or absence of caspase-8 determines the invasive and migration behavior of the cancer cells." (PMID 33026575, 2021). "Apical caspase 8 is also required for motility in mouse embryonic fibroblasts and human cancer cells but, surprisingly, its catalytic activity is not necessary." (PMID 32810419, 2020). "We recently discussed the genetic inactivation of the oncosuppressor caspase 8 (CASP8) and the death receptor FAS as strategic mechanisms cancer cells may adopt to evade apoptosis-mediated eradication by immune cells, mainly T and natural killer (NK) cells." (PMID 33193295, 2020). "We investigated the anti-cancer efficacies of PIP alone and in combination with TMZ in GBM cellsusingparameters such as cell proliferation, cellular apoptosis,caspase-8/-9/-3 activities, cell cycle kinetics, wound-healing ability, and loss of mitochondrial membrane potential (MMP)." (PMID 32693671, 2020). "CASP8, CCND1, DAPK1 and PSA are involved in pathways in cancer." (PMID 30867653, 2019). "Caspase-8 and caspase-9 knockdown in HCT116 cells inhibited caspase-3 activity confirming the involvement of both of the initiator caspases in Api and TG combination treatment-induced apoptotic cell death in cancer cells." (PMID 31673102, 2019). "Previous studies have suggested that curcumin could activate caspase-3, caspase-8, and caspase-9 and PARP protein in various cancer cell lines." (PMID 31687403, 2019). "Consistently, the levels of FLIP proteins, the main modulators of Caspase-8 enzymatic activation, are dramatically upregulated in several cancers and correlate with a poorer clinical outcome, likely related to FLIP’s cell death inhibitory function on Caspase-8." (PMID 30501030, 2018). "Using different cellular systems, it has been clearly shown that in cancer Caspase-8 can exhibit non-canonical functions, including promotion of cell adhesion, migration, and DNA repair." (PMID 30501030, 2018). "Cancer cells that express large amounts of anti-apoptotic proteins or cells infected with a virus often express non-activatable or inhibited caspase 8, which impedes apoptosis in these cells." (PMID 29028819, 2017). "We also showed that both monovalent and bivalent IAP antagonists including linker-extended compounds induced cIAP1 depletion and promoted RIPK1:caspase-8 complex formation, which correlated with their ability to degrade GFP-cIAP1 and induce cytotoxicity in cancer cell lines." (PMID 28149532, 2017).
cancer (continued). "Caspase-8 activation can induce cleavage of the ER protein BAP31 and conformational activation of Bax and Bak that is paralleled by the secretion of calreticulin (CRT), in turn able to elicit an anti-cancer immune response." (PMID 29263373, 2017). "To complement these data, we investigated the effects of docetaxel on the expression of HIF-1α target genes (Glut1, CA9, LDHA, and BNIP3) involved in the metabolism of cancer cells and pro-apoptotic genes (CASP3, CASP8, and CASP10) in siJNK2-transfected MDA-MB-231 cells under hypoxic conditions." (PMID 27263528, 2016). "In addition, sub-toxic concentrations of Iso-3 effectively decreased protein levels of cFLIP, a well-recognized inhibitor of caspase-8 activation, which is frequently overexpressed in TRAIL-resistant cancer cells." (PMID 27006469, 2016). "Given that caspase 8-mediated apoptosis is driven by the induction of DR5, we examined the levels of DR5 and found that the expression level of this protein also increased in both cancer cell lines upon treatment with dsBPT." (PMID 28033401, 2016). "Preliminary in vitro experiments confirm that UDCA can induce cancer cell apoptosis by promoting caspase-3, caspase-8, caspase-9, Bax, Fas/FasL, TRAIL, DR4, DR5 and IκB-α gene expression in cancer cells, and reduce the expression of Bcl-2, Bcl-xL, XIAP, cIAP-1, cIAP-2, survivin and NF-κB." (PMID 25951128, 2015). "The A549 cells showed increased caspase-8 activation when co-cultured with MSC-flT cells at a ratio of 4:10 (MSC: cancer cell) but not when cultured with MSC-sT cells or with MSC-GFP cells." (PMID 25888191, 2015). "CASP8 and DCC have been associated with increased aggressiveness and poor prognosis in several cancers including NB,25, 26, 27, 28 and in NB lack of CASP8 has been found to promote metastasis." (PMID 25664931, 2015). "In addition, It has been demonstrated that MAC activates cancer-associated signaling pathways through MAPK, phosphatidylinositol 3-kinase, Ras, and p70 S6 kinase, and inhibit apoptosis cancer cells by blocking FLIP, caspase-8." (PMID 26198107, 2015). "TRAIL interaction with DR4 and DR5 transduces the death receptor (extrinsic) and mitochondrial apoptosis signaling pathways through the activation of caspase-8 and caspase-10; therefore, TRAIL is usually regarded as a drug that treats cancer cells through cFLIP." (PMID 25886453, 2015). "Our data suggest that the activation of caspase-8 by GBT results in the direct activation of caspase-3, which is typical of the extrinsic apoptotic pathway, suggesting that GBT activates extrinsic apoptosis to have anti-cancer effects on A431 cells." (PMID 25241226, 2014). "To further investigate CTLA4-FasL mode-of-action in cancer cell line, we studied if CTLA4-FasL cytotoxic effect can be abrogated by the pan-caspase inhibitor (Z-VAD), caspase 8 inhibitor (Z-IETD-FMK) and caspase 9 inhibitor (Z-LEHD-FMK) on malignant cell lines positive for Fas only." (PMID 25227919, 2014). "However, several studies have illustrated that Apo2L/TRAIL resistance in cancer cell lines involves the expression of the anti-apoptotic protein c-FLIP and down-regulation of the pro-apoptotic protein caspase-8." (PMID 22666346, 2012). "The mechanisms involved here are not elucidated; however, caspase-8 is known to be under-expressed in some cancer cells as a result of DNA methylation." (PMID 22442660, 2012). "Here we investigated the possibility that dNSurR9-C84A might activate the caspase-8-mediated pathway of extrinsic apoptosis, and thereby augment the efficacy of TNF-α treatment of cancer." (PMID 20920299, 2010). "As proteosome inhibition has proven to be effective in the treatment of certain cancers, we first investigated whether MG-132 would sensitize NB7 cells re-expressing caspase-8 (NB7+Casp8 cells) to TRAIL-induced apoptosis." (PMID 20967281, 2010).
cancer (continued). "We therefore used another cell type, i.e., the HeLa carcinoma cell line, which does express endogenous caspase-8 but not caspase-10 as compared to A3 Jurkat cells." (PMID 21049020, 2010). "Additionally, it was reported that miR-19b-1 may also target caspase 8 (CASP8), death-associated protein kinase 3 (DAPK3), and programmed cell death 1 ligand 2 (PDCD1LG2), all genes known to be involved in apoptosis, further suggesting the anti-apoptotic function of the miR-17-92 cluster in cancer." (PMID 19440450, 2008). "Hence, while pomalidomide is described as pro-apoptotic through caspase-8 upregulation and inhibiting IAP-2 in cancer cell lines, in this study, we observed that pomalidomide treatment paradoxically supported cell survival through upregulating Bcl-2, improving the viability of CD4+ T cells." (PMID 39902962, 2025). "Moreover, we identify Src-dependent phosphorylation of Caspase-8 on Y380 as a key mechanism to promote mTORC1 activity and enhance NRF2 signaling in GBM cells, therefore providing evidence for a new key connecting role of Src kinase in cancer." (PMID 41053176, 2025). "In addition, we could show a significant positive correlation between CASP8 and NFE2L2 expression levels in GBM and other tumor types characterized by high Caspase-8 levels, supporting the hypothesis of an interplay between Caspase-8 and NRF2 in cancer." (PMID 41053176, 2025). "Considering the finding that tumor cell–derived factors suppressed caspase-8 and GSDMD activation in CD4+ T cells, it will be intriguing to identify and characterize these factors in the TME, which could be potential new targets for cancer immunotherapy." (PMID 40759573, 2025). "Therefore, the increase in caspase-8 and caspase-9 mRNA expression in MDA-MB-231 cells could potentially contribute to the inhibition of cancer cell growth and the induction of cell death." (PMID 38227157, 2024). "Furthermore, not only overall expression but also differential distribution of DISC function regulatory proteins such as caspase-8, cFLIP, RIP, FAP-1, etc. in charged membrane rafts additionally contributes toward supplemental barrier to apoptotic threshold in cancer cells vs. Jurkat or T cells." (PMID 37838774, 2023). "However, the Ag/MgO nanoparticles did not significantly affect caspase-8 activity in the cancer cells." (PMID 37159701, 2023). "In line with this, no caspase 8 activity was observed in SCL-1 carcinoma cells suggesting that non-functional caspase 8 might be responsible for the switch of the cell death pathway." (PMID 37210688, 2023). "Moreover, membrane cholesterol is essential for the activation and recruitment of caspase-8 and its non-apoptotic functions in cancer cells." (PMID 35712671, 2022). "While this might motivate therapeutic strategies that promote cancer cell death through ER stress-induced caspase-8 activation, it could also support the unwanted demise of non-cancer cells." (PMID 35075141, 2022). "Therefore, the presence of Caspase-8 in these cells is not a serious impediment to the development of this cancer." (PMID 36399280, 2022). "Endogenous TRAIL/death receptor-mediated caspase-8 and FADD-dependent inflammatory cytokine (e.g., CCL2/MCP-1) secretion in some TRAIL-resistant cancer cells promotes the accumulation of tumor-supportive immune cells in the cancer microenvironment, thereby encouraging cancer growth." (PMID 33810241, 2021). "Based on our knowledge about the regulating functions of caspase-8 in the cytokine secretion by cancer and non-cancer cells, immune response, and homeostasis of immune cells, we propose, that Caspase-8 is a possible new link in the interactions between the tumor and their surrounding environment." (PMID 33026575, 2021). "Indeed, FAT1, CASP8, CDKN2A, and NOTCH1 mutations were found more frequently in these tumors compared with other HNCs malignancies and other squamous non-HNCs cancers." (PMID 34440249, 2021).